DUX4L4 (double homeobox 4 like 4 (pseudogene))
Description:
May be involved in transcriptional regulation.
Gene: Unprocessed pseudogene on chromosome 4 (190,081,118 to 190,082,386, forward strand). Ensembl gene ENSG00000258834.
Subcellular location: Nucleus